UBE2T (ubiquitin conjugating enzyme E2 T)
Diseases named in the same sentence as UBE2T in open-access papers (continued):
Sharing a sentence is not in itself a finding about the gene and the disease.
tumor (continued). "In GBM, UBE2T ubiquitinates and degrades RPL6 in an E3 ligase-independent manner, thereby promoting tumor progression." (PMID 39791716, 2024). "Our findings revealed that the expression levels of the hub genes—UBE2T, KIF4A, CDCA3, and CDCA5—were correlated with various clinical aspects of HCC, including cancer stages, nodal metastasis status, tumor grade, and histological subtypes." (PMID 38890649, 2024). "Beyond common E3 enzymes, the ubiquitin-conjugating enzyme E2T (UBE2T), highly expressed in NSCLC tumor tissues, induces the ubiquitin degradation of FOXO1 and activates the downstream Wnt/β-catenin signaling pathway." (PMID 38137461, 2023). "In in vivo experiments, it was found that UBE2T knockdown inhibits the tumor growth in accumulating evidence has shown that that FBLN5, as a tumor suppressor, has LUAD." (PMID 35543375, 2022). "Analysis of the expression of E-cadherin, N-cadherin and vimentin in tumour tissue, demonstrated that EMT in tumour tissue was significantly inhibited following UBE2T silencing." (PMID 36088429, 2022). "In terms of ubiquitin-conjugating enzyme E2T (UBE2T), it was the most enriched transcript pulled down by CASC11, and has been reported to contribute to tumor growth and metastasis." (PMID 34900723, 2021). "Clinically, UBE2T overexpression in HCC was further confirmed at mRNA and protein levels and was correlated with advanced tumor stage and poor patient survival." (PMID 33542213, 2021). "Herein, we reported that NEDD4L had tumor suppressor activity to be against LUAD cells and blocked oncogenic function of UBE2T." (PMID 34838005, 2021). "We then verified the RNA-seq data by investigating the mRNA level of UBE2T in HCC tissues and the matched non-tumor tissues from our cohort and The Cancer Genome Atlas (TCGA) public database." (PMID 33087136, 2020). "By suppression of UBE2T and its downstream Akt-signaling pathway, miR-1305 impaired LCSCs’ stemness and overall HCC tumor growth." (PMID 31128423, 2019). "The nude mice injected with the cells that overexpressed miR-1305 or UBE2T were treated with LY294002 or DMSO, so as to explore the role of the Akt-signaling pathway in the regulation of miR-1305 and UBE2T in tumor formation and growth." (PMID 31128423, 2019). "We found that gross tumor volumes and weights were lower in BGC-823 KD mice than in the NC group, suggesting that UBE2T knockdown also inhibited tumor formation and progression in vivo." (PMID 28427240, 2017). "Inhibition of FA signalling components—such as FANCL, UBE2T or FANCD2—has been shown to sensitise tumour cells to crosslinking agents without inducing catastrophic genomic instability." (PMID 41486508, 2026). "UBE2T is highly expressed in UCEC and suppresses anti-tumor immune responses in UCEC patients." (PMID 39367897, 2025). "UBE2T overexpression has been indicated to enhance the PI3K-AKT pathway activity in multiple cancers, worsening tumor malignancy by increasing the phosphorylation of key components, such as PI3K, Akt, and mTOR, and regulating downstream genes associated with cell survival and anti-apoptosis." (PMID 39791716, 2024). "Second, this study only investigated at UBE2T expression level in tumor tissues and did not researched UBE2T functionality in vivo or in vitro." (PMID 36910645, 2023). "UBE2T promotes a variety of biological functions in CSCs (self-renewal, drug resistance, tumorigenicity, and metastatic ability), and UBE2T inhibition can regulate CSC-induced tumor recurrence and treatment resistance." (PMID 37053008, 2023). "Importantly, we demonstrated that UBE2T was positively correlated with p-Akt, β-catenin, CAD, DHODH, and UMPS in HCC tumor tissues." (PMID 35169125, 2022).
tumor (continued). "Furthermore, a tumorigenesis experiment in nude mice revealed that tumour growth on mice body surface and tumour tissue EMT were significantly inhibited after UBE2T gene silencing." (PMID 36088429, 2022). "Liu and his colleagues found that both the mRNA and protein levels of UBE2T were considerably greater in HCC tissues compared to nontumor tissues close to the tumor." (PMID 36245987, 2022). "UBE2T activated PI3K/Akt signaling pathway and stimulated tumor progression." (PMID 34175839, 2021). "For instance, studying more than 10,000 TCGA pan-cancer tumours, Wu and colleagues found that tumours with amplifications in DDR genes like UBE2T (Ubiquitin Conjugating Enzyme E2 T) exhibited significantly reduced mutation burden, temozolomide resistance, and worse patient survival." (PMID 34853396, 2021). "Taken together, the results of in vitro cell culture and in vivo xenograft models consistently showed that NEDD4L-mediating UBE2T degradation could inhibit the progression of LUAD cells, and ultimately reduced tumor formation." (PMID 34838005, 2021). "We investigated the expression of ASPM, CCNB2, CDCA5, KIAA0101, PRC1, and UBE2T in 12 LUAD tumor tissues and their adjacent non-malignant lung tissues." (PMID 33937050, 2021). "Based on the TCGA database, we confirmed that UBE2T was more highly expressed in the tumor areas than in the normal tissues of ICC patients." (PMID 32025379, 2020). "Depletion of UBE2T potently reduced the levels of Ki-67 and GRP78 in subcutaneous tumours." (PMID 32491994, 2020). "Suppression of UBE2T inhibited Wnt5A and WNT7B, thus inhibiting tumor growth." (PMID 28427240, 2017). "Therefore, the present study analyzed several ES datasets in the GEO data bank and discovered that UBE2T expression was observed to be considerably greater in tumor samples than in nontumor samples." (PMID 36910645, 2023). "As indicated by UALCAN database, the mRNA expression levels of HLA-A, TMEM129, UBE2D1, UBE2N, UBE2T in BCa tissue were significantly increased compared with that in normal tissue; however, the mRNA expression level of USP5 was similar between normal and tumor tissue." (PMID 34776794, 2021). "Notably, the negative correlations of four key markers, UBE2T, TEDC2, RCC1, and FAM136A, with stromal, immune, and ESTIMATE scores suggest that the high expression of these genes in LUAD may contribute to tumor growth and malignant behaviors by inhibiting the role of stromal and immune cells." (PMID 39553728, 2024).
cancer (63 papers, 2015 to 2026). A tumor composed of atypical neoplastic, often pleomorphic cells that invade other tissues. "Here, comprehensive analyses on KRASG12D-mutated PDAC models with UBE2T deletion, covering cancer initiation, progression, metastasis, and treatment resistance, have confirmed the oncogenic role of UBE2T." (PMID 39970873, 2025). "High levels of UBE2T expression are associated with poor survival outcomes, highlighting its potential as a molecular biomarker for cancer prognosis." (PMID 39791716, 2024). "Recent advances in genome-wide association studies have identified UBE2T as a predicted target of multiple miRNAs implicated in cancer progression." (PMID 39791716, 2024). "As a key member of the UBE2 family, UBE2T has recently emerged as a significant focus of research regarding its role in cancer development and progression and its underlying mechanisms." (PMID 39791716, 2024). "UBE2T is recognized as an oncogene and is associated with multiple cancer types, which make the development of UBE2T-targeted modulators an attractive focus for drug development." (PMID 39791716, 2024). "UBE2T has been implicated as an important mediator of cancer growth and metastasis in several cancer types." (PMID 36338541, 2022). "Single-cell data analysis indicated that the cell cycle is consistently and robustly associated with UBE2T across the different cancer types." (PMID 36357897, 2022). "The findings of the TIMER2 and CIBERSOR tests revealed that UBE2T was favorably linked with the amount of immune cell infiltration in the TCGA pan-cancer model." (PMID 36245987, 2022). "CancerSEA database analysis revealed that UBE2T was positively associated with the cell cycle in various cancers(r > 0.60, p < 0.001)." (PMID 36357897, 2022). "UBE2T has been reported to be associated with cancer progression and poor outcomes in several solid tumors." (PMID 33313822, 2021). "UBE2T has been associated with cancer progression and poor outcome in several solid tumors including prostate or gastric cancer." (PMID 29235520, 2017). "So far, an accurate assessment of cancer predisposition linked with UBE2T loss of function is hampered by the limited number of affected patients." (PMID 27729585, 2016). "Through its interactions with E3 ligases and other proteins, UBE2T plays a key role in several fundamental processes of cancer progression, including cell proliferation, invasion, metastasis, and cancer stem cell maintenance, and has also been linked to drug resistance in certain cancers." (PMID 39791716, 2024). "Given the critical association of UBE2T with cell cycle, combining UBE2T and its regulation on cell cycle may better predict cancer prognosis than single genes." (PMID 36357897, 2022). "Therefore, to reduce the risk of cancer, it is necessary to ensure stable levels of UBE2T and other proteins involved in the FA pathway." (PMID 33810518, 2021). "Cumulatively, we identified UBE2T as a bona fide FA gene (FANCT) that also may be a rare cancer susceptibility gene." (PMID 26085575, 2015). "Since vimentin was proved to be a regulator of cell adhesion by affecting formation and turnover adhesion structures and associated with cancer migration, we speculate vimentin may be a potential downstream protein of UBE2T in UBE2T-induced EMT and metastasis." (PMID 26308072, 2015). "Therefore, the question of whether loss-of-function mutations in UBE2T as a bona fide FA gene are associated with cancer susceptibility can only be answered in future studies involving a multi-institutional approach with large numbers of patients." (PMID 26085575, 2015). "We previously identified PGG as a highly selective inhibitor of UBE2T with potent antitumor effects in several cancers." (PMID 39970873, 2025). "UBE2T levels are often positively correlated with β-catenin in cancer, facilitating Wnt/β-catenin signaling pathway activation by ubiquitinating key proteins." (PMID 39791716, 2024).
cancer (continued). "UBE2T has been shown to activate the Wnt/β-catenin signaling pathway, which is critical in cancer progression." (PMID 39791716, 2024). "Future studies should focus on optimizing the chemical properties of UBE2T inhibitors to minimize toxicity and maximize effectiveness across various cancer types." (PMID 39791716, 2024). "Future research should integrate multi-omics data to construct a comprehensive model of the UBE2T-miRNA interaction, elucidating its mechanisms across different cancer types and identifying additional key regulators." (PMID 39791716, 2024). "Given these established findings, UBE2T holds promise as a potential therapeutic target for cancer treatment." (PMID 39791716, 2024). "This review aims to provide a detailed overview of UBE2T’s structure, functions, and molecular mechanisms involved in cancer progression as well as recent developments in UBE2T-targeted inhibitors." (PMID 39791716, 2024). "By addressing current challenges through ongoing, in-depth studies, we anticipate the development of more effective cancer therapies targeting UBE2T." (PMID 39791716, 2024). "For example, miR-1322 and miR-1305 are key regulators in HCC, targeting UBE2T to impede cancer development and progression." (PMID 39791716, 2024). "In conclusion, UBE2T’s significance in HCC lies in its role as a multifunctional oncogene that drives cancer progression, treatment resistance, and poor prognosis." (PMID 39791716, 2024). "In conclusion, UBE2T holds significant promise as a targetable oncogene for cancer diagnosis, treatment, and prognosis." (PMID 39791716, 2024). "The overexpression of UBE2T in various cancers and its involvement in critical processes such as cell proliferation, invasion, metastasis, and drug resistance make it an attractive target for cancer drug development." (PMID 39791716, 2024). "Ubiquitin-conjugating enzyme E2T (UBE2T) is a member of the E2 family and is highly expressed in various cancers." (PMID 39062505, 2024). "As an oncogene, UBE2T activates multiple cancer-promoting signaling pathways, including STAT and Wnt." (PMID 39791716, 2024). "The gene expressions of most ubiquitination-related regulators were low, while the gene expressions of UBE2C and ubiquitin-conjugating enzyme E2T (UBE2T) were extremely high in multiple types of cancer." (PMID 37540295, 2023). "Our study explored UBE2T expression and its clinic relevance across 33 cancer types in the TCGA database." (PMID 36357897, 2022). "The correlation between UBE2T and cell cycle in pan-cancer was investigated using the single-cell sequencing data in Cancer Single-cell State Atlas (CancerSEA) database." (PMID 36357897, 2022). "In colony‐formation assay, which tests the survival of cancer cells, we observed enhanced anchorage‐independent growth into semisolid medium of UBE2T overexpressing in contrast to UBE2T‐silencing cells." (PMID 34614271, 2022). "The analysis of UBE2T expression in cancer utilizing the TCGA and GTEx databases revealed a similar result as well." (PMID 36245987, 2022). "UBE2T plays a critical role in varied cancers by ubiquitinating and degrading some cancer suppressors." (PMID 35169125, 2022). "Through the PI3K/Akt signaling pathway and the Akt/GSK3β/β-catenin pathway, UBE2T is involved in the cell proliferation, migration, and invasion of cancer cells." (PMID 35035504, 2022). "After searching the website with “UBE2T”, we acquired a summary of studies with significant results for UBE2T (p < 0.001) in different types of cancer." (PMID 34257599, 2021).
cancer (continued). "And as well as the down-regulation of NEDD4L and the up-regulation of UBE2T in LUAD were independently confirmed using the cancer genome atlas (TCGA) database." (PMID 34838005, 2021). "Ramaeker showed that hypoxia can rapidly and forcefully reduce the level of UBE2T mRNA in cancer cell lines, thus greatly increasing the sensitivity of cancer cells to MMC therapy." (PMID 33810518, 2021). "The results showed that UBE2T expression was elevated in the majority of cancer cell lines compared with the normal lung epithelial cell line." (PMID 34461934, 2021). "In nasopharyngeal carcinoma, UBE2T promotes cancer cell growth via the activation of the AKT/GSK3β/β-catenin pathway." (PMID 34199813, 2021). "The upregulation of UBE2T has been reported in various cancers, such as breast, nasopharyngeal, bladder, liver, gastric, lung cancer, and aggressive clear cell renal cell carcinoma." (PMID 34199813, 2021). "UBE2T is closely related to the tumorigenesis and progress of various cancer, and its oncogenic potential is attracting more and more attention." (PMID 34257599, 2021). "UBE2T and UBE2C have been previously associated with cancer progression and poor outcome in several solid tumors, although genomic evidence in BC is recent and limited." (PMID 33671201, 2021). "Remarkably, the present work also demonstrated that higher expression of UBE2T, RFC4, POLQ, BRIP1, and H2AFX is especially associated with worse overall survival (HR > 5) in several types of cancer (Group A and D)." (PMID 34853396, 2021). "Several studies demonstrated that UBE2T expression is remarkably upregulated in several cancers, which is consistent with expression data from GEPIA database." (PMID 33323973, 2021). "Ubiquitin-conjugating enzyme E2T (UBE2T) is an oncogene, widely reported to be upregulated in multiple types of cancers." (PMID 33087136, 2020). "These three measurements, together with previous findings, indicate that suppression of UBE2T inhibits proliferation in cancer cells." (PMID 28427240, 2017). "As in the clinical samples, UBE2T expression was higher in tumors than in para-carcinoma tissues in the database." (PMID 28427240, 2017). "Overall, UBE2T is likely to exhibit diverse roles that are context dependent in different cancer types." (PMID 27729585, 2016). "In summary, a common picture emerges from these cancer studies, suggesting that increased UBE2T protein levels and presumed increase in UBE2T activity promote cell transformation and cancer growth." (PMID 27729585, 2016). "Several recent studies investigated UBE2T amplifications and UBE2T as a potential oncogene in different cancers." (PMID 27729585, 2016). "In addition, correlation analysis showed that UBE2T expression has a certain prognostic value in various cancers." (PMID 39367897, 2025). "Previous studies have reported the oncogenic role of UBE2T across multiple cancer types." (PMID 39970873, 2025). "Future development of agents that regulate miRNAs could lead to novel therapeutic strategies, offering more effective and personalized treatments for patients with UBE2T-overexpressing cancers." (PMID 39791716, 2024). "However, the specific role of UBE2T as a therapeutic target in certain cancers remains largely unexplored." (PMID 39791716, 2024). "Further investigation is needed to delineate UBE2T’s mechanisms and its roles in various cell signaling pathways, which could reveal new directions for cancer treatment." (PMID 39791716, 2024). "Therefore, a comprehensive study of UBE2T not only enhances our understanding of cancer pathogenesis but also lays a critical foundation for identifying new therapeutic targets." (PMID 39791716, 2024). "Despite the potential of UBE2T as a target in cancer therapy, significant challenges remain." (PMID 39791716, 2024). "Increasing evidence suggests that UBE2T acts as an oncogene and could serve as a promising therapeutic target in cancer treatment." (PMID 39791716, 2024).